Y_RNA (Y RNA )
Gene: Miscellaneous RNA gene on chromosome 10 (10,232,611 to 10,232,712, forward strand). Ensembl gene ENSG00000200849.
Homologues: Orthologues: chimpanzee Y_RNA (100% identical), macaque Y_RNA (92% identical). Paralogues in human: RNY3P1 (92% identical), Y_RNA (92% identical), RNY3 (91% identical), Y_RNA (91% identical), Y_RNA (90% identical), Y_RNA (89% identical), Y_RNA (88% identical), RNY3P11 (87% identical), Y_RNA (87% identical), RNY3P14 (86% identical), RNY3P2 (86% identical), Y_RNA (86% identical), and 96 more.